MUC5AC (mucin 5AC, oligomeric mucus/gel-forming)
Diseases named in the same sentence as MUC5AC in open-access papers (continued):
Sharing a sentence is not in itself a finding about the gene and the disease.
tumor (continued). "The tumor cells focally and inconsistently express MUC1, MUC2, and MUC5AC." (PMID 24084722, 2013). "CTSE expression of non-cancerous gastric mucosa adjacent to tumor lesion was evaluated, together with MUC5AC and MUC2." (PMID 23451082, 2013). "No appreciable expression of MUC2 and MUC5AC in normal and tumor tissues was detected by slot blot analyses." (PMID 16188033, 2005). "The anti-MUC2 and anti-MUC5AC antibodies stained the cytoplasm of very few tumour cells in the compact areas (data not shown)." (PMID 14760390, 2004). "In addition, tumor cells were negative for MUC5AC, whereas normal gastric epithelial cells were distinctly positive for it." (PMID 40692725, 2025). "Besides MUC2 and MUC5AC, other mucins, such as MUC1, MUC4, and MUC6, may also be dysregulated in CRC and contribute to tumor progression." (PMID 39682117, 2024). "For MUC5AC, it could be used as a poor prognostic indicator of GC, whereas a decrease of MUC6 might contribute to the malignant transformation of epithelial cells in GC and negatively correlated with lymphatic invasion and tumor size." (PMID 39886661, 2024). "However, in our study, the different MUC5AC expression has not been observed between the tumour and normal tissues as well as between diverse tumour stages." (PMID 36059804, 2022). "MUC5AC was stained only in the non-atypical foveolar epithelium that covered the tumor surface." (PMID 35029193, 2022). "Therefore, regarding MUC1, MUC2, MUC5AC, and MUC6, the most important point seems to be represented by the simultaneous and the correct use of all four of these mucins, and the integration of their expression pattern with tumor morphology." (PMID 35583805, 2022). "In conclusion the cytokeratin 7 and/or MUC5AC-positive metaplastic foci and the non-conventional growths may have a role in cancer histogenesis, while tumour cytokeratin 7 and non-cohesive histotype may also predict poor patient survival." (PMID 33963925, 2021). "In particular, CK20, MUC2, MUC5AC, MUC6 and β-catenin showed disparate expression patterns that may in part be ascribed to clinicopathologic factors such as tumor location, mucinous components, differentiation, and MSI-status, conceivably reflecting diverse underlying genetic mechanism(s)." (PMID 28824332, 2017). "Immunohistochemically, the tumor was strongly positive for keratin 7 (CK7) and pankeratin AE1/AE3, and alpha 1 antichymotrypsin; negative for synaptophysin and chromogranin A, CDx2, CK20, S100, carcinoembryonic antigen (CEA), MUC 2, MUC5AC, and somatostatin; and in part positive for CA19-9." (PMID 29145864, 2017). "These patients may be unable to respond to MUC5AC on the tumor, thus antibody levels may not correlate with clinicopathologic parameters." (PMID 16409634, 2006). "We were unable to determine the expression of MUC5AC in the tumor tissues because we could not access these tissues in the retrospective study." (PMID 16409634, 2006). "In addition, immunostaining of the same area showed that MUC5AC, which stained the gastric crypt epithelium, was diffusely positive in the intramucosal and tumor-infiltrated area, whereas MUC6 was negative to partially positive in the mucosa and positive in approximately 50% of the infiltrated area." (PMID 36781821, 2023). "This molecular-level finding accounts for the focal positivity of adenocarcinoma markers such as MUC5AC and CK7 in the setting of insufficient tissue sampling where tumor heterogeneity is not captured, potentially leading to misdiagnosis." (PMID 41333217, 2025). "Immunohistochemically, the tumor cells were positive for intestinal markers, namely MUC2 and CD10, and negative for gastric markers, namely MUC5AC and MUC6." (PMID 35898822, 2022). "Immunohistochemically, tumor cells were positive for Vimentin (mesenchyme), CK7, CK19, MUC-1, MUC-5AC, MUC-6, S-100p (focal), Ki-67 (12%), and negative for Inhibin-α, ER, CK20, CEA, and MUC-2." (PMID 33592896, 2021).
tumor (continued). "Immunohistochemically, the tumor cells were positive for MUC6 and MUC5AC and negative for intestinal-type markers such as MUC2, CD10 and CDX2." (PMID 34160413, 2021). "The glands in the margin of the tumor with low-degree atypia were positive for MUC6 and pepsinogen I but negative for MUC5AC." (PMID 31165461, 2019). "This study confirmed the expression of MUC5AC and MUC6, as well as negative expression of MUC1 and MUC2 throughout the tumour, with the final diagnosis indicating mucin producing HCC." (PMID 30875782, 2019). "Immunohistochemical analysis showed positive staining for pepsinogen I, H+/K+-adenosine triphosphatase, MUC6, and MUC5AC and negative staining for MUC2 and CD10, indicating tumor differentiation into fundic gland mucosa." (PMID 30212986, 2018). "Other promising markers (PKM2, CYFRA21.1 and MUC5AC) gave respectable classification performances in discriminating cancer cases from relevant benign controls and were independent of CRP and tumour site." (PMID 29707118, 2018). "Immunohistochemical analysis revealed that these tumor cells tested positive for CK7, CK20 (weakly), MUC5AC, MUC6, CDX2 (patchy), CEA, and CA19-9 and negative for MUC2, ER, and PgR." (PMID 25386374, 2014). "Immunohistochemical analysis (IHC) revealed that those tumor cells tested positive for CK7, CK20 (weakly), MUC5AC, CEA, and CA19-9 and negative for MUC2, MUC6, and CDX2." (PMID 25386374, 2014). "There was no binding to the insoluble mucins isolated from the tumor samples, which contain mainly MUC2 and no MUC5AC." (PMID 22563496, 2012). "The survival rates were not significantly different when patients had or had no expression of MUC1, MUC2, MUC5AC, or MUC6 in tumor." (PMID 22027009, 2011). "Essentially all the tumor cells demonstrated strong cytoplasmic MUC1 staining, but were negative for MUC2, MUC4, MUC5AC and MUC6." (PMID 20550696, 2010). "In contrast, the perihilar tumor exhibited positive for MUC1 and MUC5AC, but negative for MUC2." (PMID 37721561, 2023). "Interestingly, strong expression of Muc5ac and binding of GSII lectin were detected at 3 weeks in GLI2A-expressing tumor cells from rapamycin but not vehicle-treated mice, in keeping with H&E and PAS/Alcian blue staining." (PMID 26859571, 2016). "The tumor in our case was negative for MUC2, MUC4, MUC5AC and MUC6." (PMID 20550696, 2010). "Our evaluation with astrocytes and microglia revealed significant upregulation of MUC5AC expression upon treatment with ACM but no changes upon treatment with conditioned medium from microglia, suggesting the existence of paracrine communication between tumor cells and astrocytes." (PMID 38825648, 2024). "Among 7870 tumor samples with available TFF1 and MUC5AC data, 573 (7.3%) showed expression of both TFF1 and MUC5AC, 1391 (17.7%) showed expression of only TFF1, 325 (4.1%) showed expression of only MUC5AC, and 5581 (70.9%) showed expression of none of the two proteins (p < 0.0001)." (PMID 39410561, 2024). "In the present study, we first analyzed the tumor and adjacent non-tumor tissues of the GC patient cohorts and the biopsy tissues of the FD patients to measure the relative mRNA expression of gastric (MUC1, MUC5AC, MUC6) and intestinal (MUC2, MUC4, MUC13) mucins." (PMID 37085819, 2023). "Similarly, MUC4 but not MUC5AC was found to be overexpressed in the majority of early PanINs in a human pancreatic specimen, which predominantly consisted of small‐sized PanINs suggestive of early‐stage lesions, as well as in stage I/II of PDAC tumor specimens." (PMID 37964407, 2023).
infection (128 papers, 2010 to 2026). The state of being infected such as from the introduction of a foreign agent such as serum, vaccine, antigenic substance or organism. "MUC5AC, a major mucin, is overexpressed in chronic inflammatory airway diseases and causes airway obstruction, increases susceptibility to infection, and decreases pulmonary function." (PMID 35459887, 2022). "It was surprising that transcript levels of MUC5AC, a gel-forming mucin that is typically associated with surface gastric epithelia, but can be induced in the intestine during infection, was significantly elevated in inflamed colon." (PMID 35530046, 2022). "The development of resistance following trickle infection was associated with increased worm expulsion effector mechanisms including goblet cell hyperplasia, Muc5ac production and increased epithelial cell turn over." (PMID 31730667, 2019). "In resistant mice, IL-13 also induces goblet cell hyperplasia and elevated Muc2 and Muc5ac mucins, with deficiency of these mucins causing susceptibility to infection." (PMID 31730667, 2019). "The production of MUC5AC was linked with the elevated deposition of LeX in gastric tissue, which was stronger after 7 than 28 days post infection, p < 0.05 in Kruskal-Wallis test." (PMID 30841890, 2019). "An increased level of MUC5AC levels with r19F infection has been described in mice and associated with increased severity of RSV-infected infants." (PMID 31330970, 2019). "This is consistent with greater down-regulation of Muc5AC expression in susceptible than resistant sheep, both in a primary infection and subsequent challenge with H. contortus." (PMID 29073245, 2017). "Muc5ac, which encodes gastric M1 mucin has been reported to play a role in gastric carcinogenesis was also downregulated in response to infection with H. felis in Myd88−/− mice." (PMID 28201999, 2017). "Further, induction of IEC-specific genes associated with resistance to infection such as Muc5ac and Tslp was abrogated by VP treatment." (PMID 27598373, 2016). "Muc5AC transcription was upregulated transiently 7 days after infection in association with the development of goblet cell hyperplasia." (PMID 27335862, 2013). "Around the time of expulsion, there was a remarkable increase in Muc5ac expression in Muc2 deficient mice triggered by the infection." (PMID 25436881, 2013). "Mice deficient in Muc5ac were susceptible to infection despite generating a strong Th2 response and stayed unable to expel the parasite even after treatment with IFN-γ neutralizing antibody which further enhanced the Th2 response." (PMID 23053395, 2012). "Nevertheless, goblet-cell derived products are known to be important during T. muris infection, as demonstrated by Muc5ac deficient mice which are completely susceptible to infection." (PMID 22970115, 2012). "Analysis of cecal mucus from Muc2-deficient mice showed that Muc5ac was the only polymeric mucin present in the mucus after infection." (PMID 20138044, 2010). "As a vital component of the mucosa, H2S-mediated alterations in mucosal functions through muc5ac and muc5b downregulation and may increase the susceptibility of Atlantic salmon to secondary stress and infection." (PMID 36582361, 2022). "HRV-A16 infection caused a significant and dose-dependent increase in MUC5AC gene expression." (PMID 32637364, 2020). "The apparent down regulation of muc5ac in immune animals may however reflect an early increase in transcription caused by the challenge infection in the naïve animals." (PMID 23556022, 2013). "Interestingly, HPV may be upregulating the top MHC class I infection-permissive HSPG2 variant while downregulating the top MHC class II infection-protective MUC5AC variant." (PMID 41471728, 2025).
infection (continued). "Recently, however, two studies have reported RV-C15 – a prevalent strain in humans that may cause severe symptoms – infection of C57BL/6J mice induced the upregulation of remodeling-associated genes MUC5AC and MUC5B, elevated IL-25, IL-33, and TSLP levels, and increased numbers of lung ILC2s." (PMID 37773065, 2023). "Although further research is needed, evidence suggests that MUC5B primarily forms long bundle-like strands, whereas MUC5AC appears as thin threads or sheets, typically upregulated during infections." (PMID 41158440, 2025). "The study included several groups to analyze the specific contributions of Muc5ac in infection and disease progression." (PMID 40673273, 2025). "MUC5AC was expressed basally at lower levels, its expression increased transiently with infection, but the absolute RNA levels remained low compared to MUC5B." (PMID 40791384, 2025). "Transcriptomic and proteomic analyses of hNECs showed only moderate changes following infection, primarily characterized by increased mucus production, including upregulation of mucin MUC5AC." (PMID 40757824, 2025). "Excessive MUC5AC contributes to pathological mucus viscoelasticity, impairs clearance, and amplifies infection and inflammation." (PMID 41446468, 2025). "Though normally produced at lower levels than MUC5B, which is the dominant mucin in healthy lungs, MUC5AC is induced upon infection, and high MUC5AC levels are protective against respiratory viruses." (PMID 40035770, 2025). "The productive infection led to the reduction in Muc5ac detection and altered the expression of ZO-1, affecting the tight junctions and leading to cell aggregation suggesting possible disruption in the epithelial barrier integrity." (PMID 40733536, 2025). "In contrast to expectations, our findings indicate a significant downregulation of Muc5ac at all stages of infection compared to the control group." (PMID 40979361, 2025). "Muc5ac is the predominant gastric surface mucin and serves as a first-line defense against Hp colonization in humans, making its role in infection-related carcinogenesis particularly relevant." (PMID 40673273, 2025). "A recent study found an elevation in the transcription levels of Muc5ac in bronchial epithelial cells following infection with the Brazilian hookworm in rats." (PMID 40979361, 2025). "MUC5AC forms a protective gel on the surface of the gastric mucosa, and it increases in the intestinal tract during infection." (PMID 39204128, 2024). "Neutrophil elastase inhibitor therapy led to a non-statistically significant (P = 0.11, two-tailed Mann–Whitney U test) reduction in RV induction of BAL MUC5AC concentrations at day 4 post-infection." (PMID 38982052, 2024). "To further investigate the reduced expression of Muc5ac, we stained gastric tissue at 3 months post-infection for the Muc5ac glycoprotein by immunohistochemistry." (PMID 39588838, 2024). "Cells were allowed to differentiate for 14 to 21 days prior to infection, and differentiation was confirmed by the endpoint PCR of differentiation markers MUC5AC, CBE1, SCGB1A1, BPIFA1 and TEKT1." (PMID 39772226, 2024). "In the lung, a significant upregulation in the mRNA expression of the gel-forming mucins, Muc5ac and Muc5b, trefoil factors, Tff1 and Tff2, and Relm-β, was observed in the acute infection phase." (PMID 39596084, 2024). "Compared to sham, RV-A1 increased mRNA expression of Cxcl2, Tnf-α and Muc5ac at 24 h post-infection in placebo-treated groups." (PMID 39538325, 2024). "An association between mucus hyperproduction and infection by the genus Pseudomonas has been described, as well as a direct relationship between the overexpression of MUC-2 and MUC-5AC and the lipopolysaccharides of this bacterial family." (PMID 37373701, 2023).
infection (continued). "Patients with COPD with positive bacterial cultures during RV infection also had higher concentrations of sputum MUC5AC during infection, and their sputum MUC5AC concentrations correlated with bacterial loads determined by 16S qPCR." (PMID 35239513, 2022). "Airway respiratory syncytial viral (RSV) replication was higher in Muc5ac−/− than in Muc5ac+/+ during early infection." (PMID 35774401, 2022). "In response to infection, MUC5AC secretion was increased by 1.63-fold, a common airway epithelial response to trap pathogens." (PMID 35353667, 2022). "In naïve HAE cells, we showed that MUC5AC intracellular storage was depleted within 2 d to 3 d following infection, resulting in extracellular MUC5AC circumjacent shed viruses and sloughed cells." (PMID 35353667, 2022). "Mucin-5AC (MUC5AC) is a major gel-forming glycoprotein present in the respiratory tract epithelia that protects the mucosa from infection and chemical damage through the mucociliary system." (PMID 36339607, 2022). "Our data suggest a potential mechanism for amplification of RV-induced airway inflammation by MUC5AC through the release of ATP, a danger signal that is produced during infection and contributes to nucleotide receptor–mediated inflammatory responses." (PMID 35239513, 2022). "In order to quantify mucus metaplasia in whole lungs of control and Pou2f3-/- animals, we analyzed gene expression of goblet cell markers, Foxa3, Agr2, Muc5ac, and Muc5b, 51 days post infection." (PMID 36073526, 2022). "Exacerbation biomarkers include quantification of MUC5AB and MUC5AC degradation and increased sialyation during infection, as well as elevated granulocyte-macrophage colony-stimulating factor (GM-CSF) and neutrophil protein calprotectin." (PMID 33546140, 2021). "This indicated that MUC5B is required for MCC and controlling infections in the airways, whereas MUC5AC is dispensable." (PMID 34650550, 2021). "Clca1, Muc5ac, and Ccl11 were confirmed to be highly up-regulated during infection in WT mice but impaired in Il13−/− mice." (PMID 34127548, 2021). "The overexpression of Muc5ac in mice has been shown to reduce PR8 infection and neutrophil recruitment." (PMID 34160242, 2021). "Infection by Bp-WT, or the Bp-PT– mutant producing intact CyaA, induced similar Muc5AC and Muc5B production in polarized VA10 cell layers as the treatment with forskolin." (PMID 34445770, 2021). "BALB/c mice were infected with HMPV, and the expression of Muc1, Muc2, Muc4, Muc5ac, Muc5b, Muc15, Muc16, Muc19, and Muc20 were analyzed at 12, 24 and 48 h after infection." (PMID 32899224, 2020). "A 2.6 fold increase in mRNA levels of Muc5ac that was statistically significant (p<0.0001) when compared to the Pc(-) group was observed in day 60 of infection." (PMID 31170201, 2019). "Significantly higher levels of MUC5AC were demonstrated in animals 7 (acute phase of infection) than 28 days after the last H. pylori inoculation (chronic phase of infection) (1b ii)." (PMID 30841890, 2019). "Resistance after this infection regime is dependent on CD4+ T cells and associated with Muc5ac production and an increase in intestinal epithelial cell turnover, confirming their importance even after this multi-infection regime." (PMID 31730667, 2019). "MUC5AC belongs to the secreted mucin cluster and protects the mucosa from infection and chemical damage." (PMID 31791401, 2019). "There was a specific increase in Muc5ac expression at week 11 after trickle infection when resistance developed." (PMID 31730667, 2019). "The number of mice that displayed visible mucus and overexpressed muc5ac compared to naïve at 4 weeks post-infection was 78% of early-life infected male mice (7/9) and 15% of female mice (2/13)." (PMID 31076663, 2019). "Despite of Muc5ac being commonly found in the abomasum, its expression remained unchanged during infection." (PMID 29912166, 2018).